EPG5 (ectopic P-granules 5 autophagy tethering factor)
Diseases named in the same sentence as EPG5 in open-access papers (continued):
Sharing a sentence is not in itself a finding about the gene and the disease.
Vici syndrome (continued). "For example, Marinesco-Sjogren syndrome (MSS) and related disorders share cataracts, a skeletal muscle myopathy and, in some cases, sensorineural deafness with EPG5-related Vici syndrome, although other neurological features and the degree of multisystem involvement are usually less pronounced." (PMID 34130600, 2022). "Although many Vici syndrome mutations have been mapped, the effects of these mutations on EPG5’s structure and function are not known." (PMID 33674710, 2021). "Notably, the Epg5−/− mice showed only some features that are observed in patients with Vici syndrome." (PMID 32528724, 2020). "Sensorineural hearing loss has subsequently been reported in several cases of Vici syndrome with or without confirmed EPG5 mutations, although the detailed mechanisms underlying the sensorineural hearing loss have not been elucidated." (PMID 28492547, 2017). "Detailed review of the family histories in the 22 families remaining under follow-up revealed a large number of cases of cancer (in particular breast, stomach, and skin) and, less frequently, Parkinson’s disease in relatives of patients with EPG5-related Vici syndrome." (PMID 26917586, 2016). "A muscle biopsy is not strictly needed to establish the diagnosis, however, in cases where this was performed before Vici syndrome was suspected, a certain combination of consistent histopathological features may be supportive of EPG5 involvement." (PMID 26927810, 2016). "Moreover, we postulate that EPG5-related Vici syndrome is as much a disorder of embryonic organ development as of degeneration." (PMID 26917586, 2016). "Sensorineural hearing loss was recognized in an isolated case in 2010 and has been subsequently reported in other cases of Vici syndrome with or without confirmed EPG5 mutations." (PMID 26927810, 2016). "Although other features are less consistently associated, virtually any organ system – including thyroid, lungs, liver and kidneys – may be affected in Vici syndrome patients, in keeping with the ubiquitous expression of the EPG5 protein and its fundamental biological importance." (PMID 34130600, 2022). "In addition to the five features that have previously been considered to be diagnostic, we identified three additional features that are equally consistent in EPG5-related Vici syndrome and will help clinicians to make more informed decisions regarding genetic testing in suspected cases." (PMID 26917586, 2016). "The tethering and fusion of autophagosomes and lysosomes are mediated by two regulatory factors, EPG5 and INPP5E, which are known to be responsible for two human hereditary disorders, Vici syndrome and Joubert syndrome, respectively." (PMID 32528724, 2020). "The epg5 knockout mice show cellular defects, including SQSTM1/p62 (sequestosome 1) aggregates accumulation and ubiquitin-positive inclusions formation in neurons and glial cells, along with the key features of Vici syndrome." (PMID 40152605, 2025). "Here we report 3 patients with EPG5-related Vici syndrome and not previously recognized pancreatic involvement, ranging from otherwise asymptomatic amylase elevations to acute pancreatitis and pancreatic insufficiency." (PMID 41312553, 2025). "The relative frequency of specific clinical features, natural history, overall prognosis, and genotype–phenotype correlations have not yet been reported for EPG5-related Vici syndrome." (PMID 26917586, 2016).
Immunodeficiency (9 papers, 2016 to 2026). Failure of the immune system to protect the body adequately from infection, due to the absence or insufficiency of some component process or substance. "Mutations in EPG5 (ectopic P-granules autophagy protein 5 homolog) gene results in the recessive multisystem disorder Vici syndrome characterized by congenital cataract, callosal agenesis, combined immunodeficiency, cardiomyopathy, and hypopigmentation." (PMID 37034386, 2023).
cardiomyopathy (6 papers, 2016 to 2024). A disease of the heart muscle or myocardium proper. "Whilst, not unexpectedly, most truncating EPG5 mutations were associated with a severe phenotype, the only recurrent missense mutation in our series, p.Gln336Arg, was associated with a reduced likelihood of cataracts or a cardiomyopathy, and a relatively longer life expectancy." (PMID 26917586, 2016).
cataract (6 papers, 2014 to 2022). Partial or complete opacity of the crystalline lens of one or both eyes that decreases visual acuity and eventually results in blindness. "A first-degree relative of one of the EPG5-mutated patients developed early-onset cataracts, and vitiligo was occasionally reported." (PMID 26917586, 2016).
microcephaly (6 papers, 2016 to 2025). A congenital or acquired developmental disorder in which the circumference of the head is smaller than normal for the person's age and sex. "Two siblings from a consanguineous family (145.1 and 145.2) were homozygous for the EPG5 variant p.Pro1309Leu, and presented with a global neurodevelopmental disorder, hypopigmentation, seizures, spasticity, failure to thrive, and microcephaly." (PMID 41053928, 2025). "Patient 143.1 was homozygous for the EPG5 variant p.Ser547Phe, and showed congenital microcephaly, spasticity, nystagmus at birth, and seizures from infancy on the background of a global neurodevelopmental disorder with moderate to severe intellectual disability." (PMID 41053928, 2025).
amyotrophic lateral sclerosis (5 papers, 2016 to 2025). Amyotrophic lateral sclerosis (ALS) is a neurodegenerative disease characterized by progressive muscular paralysis reflecting degeneration of motor neurons in the primary motor cortex, corticospinal tracts, brainstem and spinal cord. "A dosage effect is also suggested by the previous preliminary observation of movement disorders in heterozygous EPG5 variant carriers in a small number of families, and the suggestion of EPG5 variants as a modifying factor in Alzheimer's disease and amyotrophic lateral sclerosis." (PMID 41053928, 2025). "Epg5-deficient mice also exhibit selective damage of cortical layer 5 pyramidal neurons and spinal cord motor neurons, the key manifestations of amyotrophic lateral sclerosis (ALS)." (PMID 40152605, 2025).
epilepsy (4 papers, 2016 to 2025). A brain disorder characterized by episodes of abnormally increased neuronal discharge resulting in transient episodes of sensory or motor neurological dysfunction, or psychic dysfunction. "Two-thirds of patients had a severe seizure disorder, placing EPG5 within the rapidly expanding group of genes associated with early-onset epileptic encephalopathies." (PMID 26917586, 2016). "A detailed analysis of EPG5‐related epilepsy has been reported elsewhere." (PMID 41053928, 2025).
Parkinson disease (4 papers, 2016 to 2026). A progressive degenerative disorder of the central nervous system characterized by loss of dopamine producing neurons in the substantia nigra and the presence of Lewy bodies in the substantia nigra and locus coeruleus. "Less-severe EPG5 pathogenic variants have recently been linked to rare familial forms of Parkinson's disease, suggesting deficits in EPG5 function drive a range of neurodegenerative disorders." (PMID 41618100, 2026). "Monogenic defects in mitophagy, such as PINK1 or Parkin deficiency, are associated with early‐onset parkinsonism, and there is a significant phenotypic overlap with our EPG5‐mutated patients with parkinsonism." (PMID 41053928, 2025). "A 14‐year‐old girl (case 114.1) compound heterozygous for EPG5 variants p.Arg1501Trp and p.Thr1994Ala presented with generalized dystonia and parkinsonism with cognitive decline followed by rapid deterioration and death at the age of 16 years." (PMID 41053928, 2025). "A 14‐year‐old girl (case 96.1) compound heterozygous for EPG5 variants p.Val464Ala and p.Tyr855Ter presented with severe progressive fluctuating generalized dystonia, parkinsonism, and cognitive decline on the background of moderate neurodevelopmental delay." (PMID 41053928, 2025). "Early‐onset parkinsonism as part of EPG5‐RDs corresponds to earlier preliminary observations of an apparently increased Parkinson's disease risk in heterozygous EPG5 variant carriers." (PMID 41053928, 2025). "The cell line from the EPG5‐mutated patient with parkinsonism was chosen to investigate for clear mitophagy defects as a cause for potential neurodegeneration." (PMID 41053928, 2025). "More specifically, we investigated a fibroblast cell line from a 22‐year‐old patient with parkinsonism and a homozygous EPG5 variant in c.6861_6862insTTTCCAACAGCAGAGTTC, p.Phe2287_Leu2288insPheProThrAlaGluPhe." (PMID 41053928, 2025). "In Caenorhabditis elegans, EPG5 knockdown caused motor impairments, defective mitophagic clearance, and changes in mitochondrial respiration comparable to observations in C. elegans knockdown of parkinsonism‐related genes." (PMID 41053928, 2025). "Notably, we were able to show α‐synuclein overexpression through SNCA mRNA abundance in the cell line from the patient with EPG5‐related parkinsonism, as well as in the 2 cell lines from EPG5‐mutated patients with milder, primarily neurodevelopmental disorders." (PMID 41053928, 2025). "We argue that the adolescent‐onset parkinsonism seen at the milder end of the EPG5‐related spectrum may be a result of defective mitochondrial clearance considering that monogenic disorders in mitophagy genes show similar dystonia‐parkinsonism phenotypes." (PMID 41053928, 2025). "Of note in this context, EPG5 (known as KIAA1632 at the time) was initially found to be mutated in breast cancer, and there is a precedent of an increased frequency of Parkinson’s disease in families with lysosomal storage disorders." (PMID 26917586, 2016). "The impaired mitophagy observed in EPG5‐mutated patient cells also closely mimics mitochondrial abnormalities seen in a mouse model of GBA‐associated Gaucher disease, a lysosomal storage disorder associated with Parkinson's disease in heterozygous GBA variant carriers." (PMID 41053928, 2025). "As a notable finding in this study, we investigated a fibroblast cell line from a patient with EPG5‐related parkinsonism that showed defects in PINK1/Parkin‐mediated mitophagy, reiterating our findings in cell lines from milder EPG5‐related disorders." (PMID 41053928, 2025).
Alzheimer disease (2 papers, 2018 to 2025). A progressive, neurodegenerative disease characterized by loss of function and death of nerve cells in several areas of the brain leading to loss of cognitive function such as memory and language. "Seven EPG5 SNPs were also recently associated with the risk of Alzheimer’s disease and another eight associated with the age of onset of Alzheimer’s disease." (PMID 30348966, 2018).
influenza (2 papers, 2022 to 2025). An acute viral infection of the respiratory tract, occurring in isolated cases, in epidemics, or in pandemics; it is caused by serologically different strains of viruses (influenzaviruses) designated A, B, and C, has a 3-day incubation period, and usually lasts for 3 to 10 days. "Deletion of autophagy genes including Epg5, Atg14, FIP200, Atg5 and Atg7 led to influenza resistance." (PMID 36042265, 2022).
lung carcinoma (2 papers, 2019 to 2022). "At the same time, lower level of EPG5 expression was significantly correlated with lower survival of lung cancer patients, which was analyzed in KM-plotter database." (PMID 31410206, 2019). "Similarly, c-Myc/miR-150/EPG5 control autophagy response to promote lung cancer, and G9a regulates c-Myc-induced autophagy in glioblastoma cells." (PMID 36072894, 2022). "Furthermore, the expression of EPG5 was correlated with longer survival of lung cancer patients and silencing EPG5 significantly promoted NSCLC cells growth, and attenuated the pro-tumor growth effect of miR-150 in vitro and in vivo." (PMID 31410206, 2019).
acute pancreatitis (1 paper, 2025). An acute inflammatory process that leads to necrosis of the pancreatic parenchyma. "Defective autophagy plays a critical role in mitochondrial dysfunction observed in acute pancreatitis models, through its effects on mitophagy, an essential process for mitochondrial quality control that has also recently been demonstrated to be affected in EPG5-related disorders." (PMID 41312553, 2025). "Here we present 3 patients with an EPG5-related disorder and not previously reported pancreatic involvement, ranging from otherwise asymptomatic amylase elevations to acute pancreatitis and pancreatic insufficiency." (PMID 41312553, 2025).
Danon disease (1 paper, 2016). A lysosomal glycogen storage disease characterized by severe cardiomyopathy and variable degrees of muscle weakness, frequently associated with intellectual deficit. "The defects implicated in Danon disease and X-linked myopathy with excessive autophagy (MEAX), in particular impaired autolysosomal fusion and defective intralysosomal digestion, affect the same part of the autophagy pathway also affected in EPG5 deficiency." (PMID 26917586, 2016).
ischemia (1 paper, 2021). A hypoperfusion of the BLOOD through an organ or tissue caused by a PATHOLOGIC CONSTRICTION or obstruction of its BLOOD VESSELS, or an absence of BLOOD CIRCULATION. "EPG5 is reduced in rodent models of ischemia and mediates neuronal survival and normal functioning." (PMID 33964983, 2021).
Neurodevelopmental delay (1 paper, 2025). "Two siblings homozygous for the EPG5 variant p.Phe2004Ser had a background of global severe neurodevelopmental delay." (PMID 41053928, 2025).
pancreatitis (1 paper, 2025). Inflammation of the pancreas. "A literature review was done by searching the terms “autophagy”/”EPG5”/”Rab7”/other autophagy-linked genes identified in the search AND “pancreas”/”pancreatitis” in PubMed, for papers published between 01/01/1980 and 01/06/2024." (PMID 41312553, 2025).
retinal degeneration (1 paper, 2025). Degeneration of the retina. "Potential interacting molecules involved in retinal degeneration or visual cycle, including MINDY3, EPG5, miR‐548b‐3p, OTX2, miR‐519d, LRAT, and NR2E3, were selected based on the STRING and miRDB (MicroRNA Target Prediction Database) databases." (PMID 40956390, 2025).
Skeletal myopathy (1 paper, 2022). "In contrast to EPG5-related Vici syndrome, a skeletal myopathy has not been reported in any of the other congenital disorders of autophagy yet." (PMID 34130600, 2022).
ZTTK syndrome (1 paper, 2025). "In 2/61 cases, RNA-seq revised diagnoses (EPG5 to LZTR1 in an individual with a Noonan syndrome-like disorder) and discovered an additional relevant gene (CEP120 in addition to SON in an individual with ZTTK syndrome)." (PMID 40593860, 2025).
neurodevelopmental disorder (5 papers, 2016 to 2025). A behavioral and cognitive disorder with onset during the developmental period that involves impaired or aberrant development of intellectual, motor, or social functions. "Where the initial diagnosis was a non‐specific neurodevelopmental disorder (n = 150), EPG5 variants were bi‐truncating in 22%, mixed in 13%, and bi‐missense in 65% of patients." (PMID 41053928, 2025). "Moreover, many neurodegenerative diseases but in particular neurodevelopmental disorders such as EPG5-related Vici syndrome, display defects in the actual autophagy cycle, leading to a slower or impeded clearance." (PMID 34130600, 2022).
movement disorder (3 papers, 2022 to 2025). Neurological conditions resulting in abnormal voluntary or involuntary movement, which may impact the speed, fluency, quality and ease of movement. "In one of our previous studies, we observed that heterozygous EPG5 pathogenic variant carriers may have an increased risk of movement disorders, indicating a gene dosage effect on EPG5 function." (PMID 41053928, 2025).
myopathy (3 papers, 2022 to 2025). A disease of the muscle in which the muscle fibers do not function properly. "Epg5 knockout mice have been shown to display some phenotypic similarities with VS patients, including corpus callosum changes and myopathy." (PMID 41053928, 2025).
neurodegenerative disease (3 papers, 2016 to 2022). A disorder of the central nervous system characterized by gradual and progressive loss of neural tissue and neurologic function. "Neurological progression over time indicates an intriguing link between neurodevelopment and neurodegeneration, also supported by neurodegenerative features in epg5-deficient Drosophila, and recent implication of other autophagy regulators in late-onset neurodegenerative disease." (PMID 26917586, 2016). "To further investigate the functional effects of EPG5 deficiency on autophagy and neuronal function, we studied the effects of conditional EPG5 knockdown in neurons of the fruit fly, Drosophila melanogaster, a widely used model for the study of neurodegenerative disease." (PMID 26917586, 2016). "Interestingly, EPG5 has been shown to be a modifier of this DPR toxicity, emphasizing again the role of autophagy in neurodegenerative diseases." (PMID 34130600, 2022).
infection (2 papers, 2021 to 2025). The state of being infected such as from the introduction of a foreign agent such as serum, vaccine, antigenic substance or organism. "VS is caused by recessive mutations in EPG5, encoding a tethering factor with important roles in autophagy, an essential cellular homeostatic mechanism involved in metabolic adaptation, infection defence and quality control of proteins and organelles." (PMID 41312553, 2025).
neurological disease (1 paper, 2025). "A novel Epg5 knock‐in mouse model of a recurrent EPG5 missense variant featured motor impairments and defective autophagy in brain areas particularly relevant for the neurological disorders in milder presentations." (PMID 41053928, 2025). "Our findings illustrate a lifetime neurological disease continuum associated with pathogenic EPG5 variants, linking neurodevelopmental and neurodegenerative disorders through the common denominator of defective autophagy." (PMID 41053928, 2025). "We next investigated an in vivo animal model with an EPG5 missense variant to investigate what aspects of the neurological disorders in humans carrying recessive EPG5 missense variants could be replicated in mice." (PMID 41053928, 2025).
tumor (1 paper, 2019). "In this study, we demonstrate that miR-150 inhibits autophagic flux, increases cellular ROS level and DNA damage, promotes NSCLC progression through repressing EPG5, which is shown to be a novel tumor suppressor in NSCLC by our evidence." (PMID 31410206, 2019). "Using antagomir-150, a chemically stabilized miR-150 inhibitor, markedly inhibited control cells; while silencing EPG5 attenuated the anti-tumor effect of antagomir-150 in shEPG5 cells in vitro." (PMID 31410206, 2019). "Taken together, in this study, we revealed that high expression of miR-150 notably inhibited the fusion of autophagosomes with lysosomes through repressing the expression of EPG5, which played a tumor-suppressor role in NSCLC cells." (PMID 31410206, 2019). "On the contrary, tail intravenous injection of agomir-150, a chemically stabilized miR-150 mimic, dramatically increased miR-150 expression in tumors, and notably promoted tumor growth in EPG5-shNC harboring mice without causing any change in EPG5-sh3 xenograft." (PMID 31410206, 2019). "Therefore, we defined EPG5 as a new functional target of miR-150 and as a novel NSCLC tumor-suppressor." (PMID 31410206, 2019).